RNU6-747P (RNA, U6 small nuclear 747, pseudogene)
Gene: Small nuclear RNA gene on chromosome 1 (243,081,156 to 243,081,259, reverse strand). Ensembl gene ENSG00000212230.
Homologues: Orthologues: chimpanzee U6 (100% identical), macaque U6 (92% identical), pig U6 (83% identical), pig U6 (79% identical), dog U6 (78% identical). Paralogues in human: RNU6-1319P (100% identical), RNU6-241P (100% identical), RNU6-1076P (99% identical), RNU6-1100P (99% identical), RNU6-1118P (99% identical), RNU6-1217P (99% identical), RNU6-355P (99% identical), RNU6-447P (99% identical), RNU6-785P (99% identical), RNU6-791P (99% identical), RNU6-860P (99% identical), U6 (99% identical), and 1287 more.